AQP4 (aquaporin 4)
Diseases named in the same sentence as AQP4 in open-access papers (continued):
Sharing a sentence is not in itself a finding about the gene and the disease.
brain tumors (49 papers, 2002 to 2025). "In a brain tumor edema model involving stereotactic implantation of melanoma cells, AQP4-deficient mice showed higher ICP and accelerated neurological deterioration." (PMID 39944892, 2025). "In fact, in high-grade brain tumors, AQP4 shows a loss of its polarized distribution at the tips of astroglial pedicels, which can contribute to increased tumor cell migration (Vandebroek and Yasui (2020))." (PMID 37895420, 2023). "The glial membrane water channel AQP4 holds pathological implications in the brain tumour context as it is involved in tumour-associated oedema, tumour cell invasion and proliferation." (PMID 36071478, 2022). "This study opens a new perspective on the role of AQP4 in the brain tumour microenvironment associated with the EV-dependent communication mechanism." (PMID 36071478, 2022). "AQP4 is also important for the removal of water in vasogenic edema, caused by brain tumor and brain abscess." (PMID 30483388, 2018). "Vasogenic edema has a great effect on the morbidity and mortality associated with malignant brain tumors, and AQP4 has a major role in its pathogenesis." (PMID 27367682, 2016). "Moreover, edema has also been linked to increased levels of AQP4, in part because in brain tumors, water moves into the brain through a leaky blood–brain barrier via a bulk fluid flow mechanism." (PMID 38263015, 2024). "In vascular cerebral edema mouse models such as cortical freezing, brain tumors, and intracranial rehydration fluid, AQP4-deficient animals demonstrated significantly more brain swelling than wild-type mice, most likely because AQP4 in wild mice expedited the outflow of water from edema tissue." (PMID 36204139, 2022). "Thus, it seems that BBB disruption associated with brain tumors and other forms of brain insults up-regulate the expression of AQP4." (PMID 33208141, 2020). "GS (mainly via the AQP-4 channel) is also proposed to play a role in the pathophysiology, clinical manifestations, and complications of brain tumors." (PMID 40464180, 2025). "The blood–brain barrier turns leaky in brain tumors, allowing the influx of water, which then exits the brain through the AQP4-rich glia limitans lining the brain ventricles and the brain surface." (PMID 38263015, 2024). "The relationship between AQP4 and brain tumor characteristics, such as invasion and migration, has been established." (PMID 38539556, 2024). "CNS edema is frequently accompanied by brain tumors, and understanding of the role of AQP4 during CNS water transporter and lymphatic flow has made significant progress in the last decade." (PMID 35847914, 2022). "In particular, aquaporin-1 (AQP1) is important in tumour growth and spread and AQP4 protein has a crucial role in vasogenic oedema that increases the mortality related to brain tumours." (PMID 36071478, 2022). "We should pay close attention to the various unresolved questions regarding AQP4 functions in brain tumors and various other CNS neurological diseases." (PMID 36523816, 2022). "Several studies suggested a crucial role of AQP1 and AQP4 in the vascular permeability of edematous brain tumors." (PMID 35847914, 2022). "On the basis of expression profiles of brain tumor and its normal expression in astrocytes, in addition to the distinctive patterns of chemo and radiation of therapy, the strategy of designing AQP4-targeted therapy can be challenging." (PMID 35847914, 2022). "Previously, AQP4 was well-descripted as brain-specific regulator and in recent years, there has emerged an intriguing and surprising link between AQP4 and brain tumors." (PMID 36523816, 2022). "A study in several types of edematous human brain tumors has also revealed the alterations of AQP-4 in reactive astrocytes." (PMID 33563219, 2021). "This study is the first to comprehensively examine AQP4 gene expression in human brain tumors available in the TCGA and GEO databases as well as its relationship to protein modulation, genetic alteration and other gene expression." (PMID 34113257, 2021).
brain tumors (continued). "In this context, it is the leaky vascular bed that is responsible for vasogenic edema formation in brain tumors where AQP4 channels are recruited to maintain cerebral water balance." (PMID 33538957, 2021). "In the present study, we showed the potential action of AQP4 on producing edema in brain tumors due to accumulation of bradykinin." (PMID 32182968, 2020). "Knocking-down BDKRB1 simultaneously inhibited AQP4 expression and migration and invasion by human brain tumor cells." (PMID 32182968, 2020). "AQP4 proteins are involved in cell migration, angiogenesis, and edema formation in human brain tumors." (PMID 31683640, 2019). "These properties of AQP4 appear unrelated to the canonical and well-established role of AQP4 in edema formation and absorption, suggesting this protein as novel therapeutic target for treating brain tumors." (PMID 28423683, 2017). "AQP4 is also upregulated in brain tumors and a clear correlation has been found between AQP4 levels and patients’ survival time." (PMID 29261132, 2017). "We analyzed aquaporin 4 and -1 expression in subependymomas, benign and slow growing brain tumors WHO grade I. Ten subependymoma cases were investigated, five of the fossa inferior and five of the fossa superior." (PMID 26115524, 2015). "AQP1, AQP4, and AQP9 are mainly expressed in brain tumor, and among them AQP4 is particularly important due to its up-regulation in malignant tumor and brain edema." (PMID 22145049, 2011). "Further studies are needed to clarify the mechanisms responsible for the upregulation of AQP1 (present study) and AQP4 expression in brain tumours and the contribution of these water channels to brain tumour oedema." (PMID 12237771, 2002). "Similarly, AQP4 knockout mice had worse outcomes and approximately 2-fold greater edema in a cortical freeze injury and in a brain tumor implantation model." (PMID 40943104, 2025). "Furthermore, also in our previous work, AQP4 has been identified as one of the most promising biomarkers of brain tumors." (PMID 38539556, 2024). "Notably, of these 50 highlighted proteins, 12 (24%) overlap with core panel proteins identified as the most promising biomarkers of brain tumors in our previous work, including AQP4." (PMID 38539556, 2024). "AQP4 may have a role in the migration and invasion of brain tumours, and it may fast-track tumour migration by enabling the quick alterations in cell volume that occur when cell shape alters." (PMID 38336645, 2024). "An increased brain water accumulation and intracranial pressure were observed in AQP4-null mice compared with wildtype mice with brain tumors, brain abscesses, focal cortical freeze injury, and after direct infusion of normal saline into brain extracellular space." (PMID 35260880, 2022). "However, it has recently been suggested that AQP4 also plays an important role in brain tumor development and progression, although these studies are still in the early stage." (PMID 35847914, 2022). "This dual function of AQP4 may play an important role in any processes involving brain swelling, including brain tumors, which may be extended to metastatic tumors to the brain." (PMID 35847914, 2022). "We can conclude that AQP4 could play a key role in the malignant proliferation and immunological regulation of human brain tumor." (PMID 36523816, 2022). "Screening for specific inhibitors of AQP4 may illuminate the design of novel mechanism-based therapies for brain tumors." (PMID 34113257, 2021). "We hypothesized that AQP4 could also be the regulatory factors of various immune checkpoints in brain tumors, such as TIM-3 (HAVCR2), PD-L1 (CD274), PD-L2 (PDCD1LG2), and CEACAM1." (PMID 34113257, 2021). "Enhanced expression of AQP4 has also been demonstrated in human brains with infarction, in various inflammatory conditions including human immunodeficiency virus encephalitis and progressive multifocal leukoencephalopathy and some brain tumor series." (PMID 32998402, 2020).
brain tumors (continued). "AQP4-null mice with edematous brain tumors showed increased intracranial pressure and more neurological complications compared to wild-type, indicating AQP4 may have a protective effect in this case." (PMID 28036023, 2016). "AQPs may be regulated under pathological conditions: For example AQP1 and AQP4 are strongly upregulated in brain tumors and in injured brain tissue, AQP5 is down-regulated during ischemia but up-regulated following brain injury." (PMID 24817998, 2014). "The different redistribution patterns of Kir4.1 and AQP4 in low- and high-grade human brain tumors also supports the hypothesis of separated mechanisms for the clustering of Kir4.1 and AQP4." (PMID 17356517, 2007). "Notably, it was shown that inhibition of AQP4 mitigates the progression of brain tumors." (PMID 38539556, 2024). "However, the mechanism of AQP4 involvement in brain tumors is still under investigation." (PMID 22808259, 2012). "AQP1, AQP4 and AQP9 are expressed in brain tumours, and AQP4 expression increases with the severity of brain oedema." (PMID 35178393, 2022). "Water channel molecule, aquaporin-4 (AQP4), has been suggested to play a role in BBB disruption in tumors as cerebral edema is an important sign of brain tumor." (PMID 33208141, 2020). "Hence, AQP4 may participate in the development of brain tumors." (PMID 32182968, 2020). "In brain tumors, AQP1 and AQP4 expression is upregulated with the malignancy grade." (PMID 38476871, 2024). "While production of brain edema in tumors is independent of AQP4, expression is upregulated in edematous brain tumors and does not exclusively localize to astrocytic end-feet in these tumors." (PMID 28036023, 2016). "Brain tumour models comparing wild-type mice with AQP1 and AQP4 knockout mice may shed light on the contribution of these water channels to brain tumour oedema." (PMID 12237771, 2002). "This could be an explanation for our observation that brain tumor cell lines, which were not able to express AQP4 in vitro, re-expressed AQP4 after implantation into the brain, but not if implanted subcutaneously into the flank." (PMID 22590566, 2012). "Indeed, AQP4 deletion does not affect the brain morphology and baseline intracranial pressure under physiological condition, while it worsens vasogenic edema in a freeze-injury model and a brain tumor edema model." (PMID 31178701, 2019).
systemic lupus erythematosus (42 papers, 2011 to 2025). An autoimmune multi-organ disease typically associated with vasculopathy and autoantibody production. "Given the association of NMOSD with lupus, evaluation of anti-AQP4/MOG antibodies is important and may potentially guide treatment." (PMID 29928273, 2018). "Approximately 30-40% of AQP4-IgG seropositive patients exhibit concurrent autoimmune disorders, with systemic lupus erythematosus (SLE) being the most prevalent comorbidity." (PMID 40491913, 2025). "Conversely, AQP4-ON patients more frequently had comorbidities such as Sjögren’s syndrome and systemic lupus erythematosus, along with abnormalities in antinuclear antibody spectrum immunological indicators." (PMID 38988608, 2024). "Six patients, all among the AQP4+ patients, had co-morbid rheumatologic disease including systemic lupus erythematosus (n = 4), Sjögren’s syndrome (n = 1), and rheumatoid arthritis (n = 1)." (PMID 38256489, 2024). "In our study, three MOG-ON patients were either pregnant or postpartum, while one AQP4-ON patient was in the postpartum period and had a history of systemic lupus erythematosus." (PMID 38988608, 2024). "A higher percentage of AQP4-ON patients had comorbidities such as Sjögren’s syndrome and systemic lupus erythematosus compared to MOG-ON patients (6/20 [30.0%] vs. 0/26[0.0%]; p = 0.004)." (PMID 38988608, 2024). "In line with ibrutinib, the first generation BTK inhibitor, which blocks plasmablast generation and production of autoantibodies in systemic lupus erythematosus, zanubrutinib reduced AQP4–IgG production in vitro." (PMID 38129902, 2023). "These antibodies can be associated with other neurological syndromes such as intractable hiccups and vomiting due to lesions in the area postrema, highlighting the broadening spectrum of AQP4-associated neurological disease, both with and without lupus." (PMID 29928273, 2018). "Only one patient had significant comorbidities, being diagnosed also with systemic lupus erythematosus (SLE), Sjogren syndrome, and positive antiaquaporin-4 antibodies (AQP4)." (PMID 33728176, 2021). "In the AQP4-NMOSD cohort, the most common AIDs observed were autoimmune thyroiditis (n = 18), followed by systemic lupus erythematosus (n = 8), myasthenia gravis (n = 7), and rheumatoid arthritis (n = 7), and Sjögren’s syndrome (n = 5)." (PMID 40495001, 2025). "Notably, the presence of AQP4-Abs has already been described in the context of systemic autoimmune diseases such as adult-onset systemic lupus erythematosus (SLE), but their presence in children and adolescents with jSLE is still under investigation." (PMID 37208665, 2023). "Moreover, a significant causal effect has been found between AQP4-IgG positive NMO and recognized risk variant for systemic lupus erythematosus (SLE)." (PMID 34675927, 2021). "The identification of longitudinally extensive spinal lesions, particularly when accompanied by brainstem involvement, should raise suspicion for NMOSD even in patients with a prior lupus diagnosis or negative anti-AQP4 antibody test." (PMID 41431554, 2025). "Antibodies against AQP4 can be generated in people with lupus without an opticospinal inflammatory event." (PMID 29928273, 2018). "Systemic lupus erythematosus, Sjögren syndrome, and myasthenia gravis, which are common in AQP4-IgG-positive NMOSD, were absent in all of our MOG-IgG-positive patients." (PMID 27793206, 2016). "Nine AQP4-positive patients reported a family history of non-CNS autoimmunity including rheumatoid arthritis (N = 7; including the mother of the two patients with paternal MS), systemic lupus erythematosus (SLE; 2), and diabetes mellitus." (PMID 22260418, 2012). "AQP4-IgG related NMOSD may coexist with other autoimmune diseases, including organ-specific disorders (e.g., myasthenia gravis, thyroid disease, celiac disease) and non-organ-specific disorders (systemic lupus erythematosus, Sjögren syndrome)." (PMID 32671002, 2020).
systemic lupus erythematosus (continued). "AQP4-IgG antibodies were absent in two patients with NMO (4%), 21 patients with HR-NMO (40%), 31 CIS patients (97%) and all patients with ADEM and MS as well as all controls (CTRL) including patients with systemic lupus erythematosus (SLE), other neurological diseases (OND) and healthy individuals." (PMID 22204662, 2011).
depression (41 papers, 2015 to 2026). "Genetic variants in AQP4 are also linked to increased risk for depression, implicating this astrocytic water channel in the disorder’s pathophysiology." (PMID 40725164, 2025). "This has been accompanied by widespread loss and distribution of AQP4 in astrocytes, suggesting glymphatic system disruptions in animal models of depression." (PMID 37760916, 2023). "This and previous studies have demonstrated that impaired glymphatic function in depression models arises in conjunction with decreased astrocyte numbers and loss of AQP4 polarization." (PMID 37802998, 2023). "On the other hand, dysfunctional AQP-4 channels were associated with depression, insomnia, dysfunctional synaptic plasticity, and impaired fear extinction." (PMID 34776871, 2021). "We found that age, number of clinical attacks, disability, pain interference, anxiety, and depression were associated with fatigue (in a positive direction) in AQP4‐Ab patients." (PMID 32187851, 2020). "A reduced density of AQP4-positive endfeet in the orbitofrontal cortex is associated with major depressive disorder in humans and the antidepressant fluoxetine enhances the endfeet density in an AQP4-dependent manner." (PMID 30563176, 2018). "In depression, AQP4 dysfunction has been implicated in both clinical and preclinical studies." (PMID 41462664, 2025). "Studies using preclinical models of chronic psychological stress and post-mortem tissue from patients with major depressive disorder (MDD) have reported reductions in AQP4, loss of perivascular astrocytic processes, and atrophy of astrocytes in the prefrontal cortex (PFC)." (PMID 38798398, 2024). "Consequently, psychological disorders, mainly depression, cause depolarized expression of AQP4, further leading to dysfunction of the glymphatic system and contributing to the development of AD." (PMID 38270115, 2024). "Preclinical studies frequently report AQP4 dysregulation in depression models, characterized by reduced perivascular expression and impaired polarization in mood-relevant brain circuits." (PMID 41683659, 2026). "This review synthesizes emerging evidence highlighting the multifaceted role of Aquaporin-4 (AQP4), the central nervous system's predominant water channel, in the pathophysiology of depression." (PMID 41683659, 2026). "In the context of depression, preclinical and clinical studies have suggested a dysfunctional activity of AQP4." (PMID 40650814, 2025). "Another study demonstrated that melatonin rescued depressive symptoms in mouse model of depression by modulating Per2 circadian protein expression, maintaining astrocytic AQP4 polarization circadian rhythm, and restoring glymphatic function." (PMID 40917304, 2025). "Astrodegenerative changes, including decreased expression of astrocyte markers such as aquaporin-4 (AQP4) and connexins, have been reported in animal models of stress-induced depression." (PMID 40016145, 2025). "Although the underlying mechanisms are not fully understood, these findings highlight the direct relationship between AQP4 activity and depressive behaviour, pointing out astrocytic AQP4 as a potential mechanistic target for the pathophysiology of depression." (PMID 40650814, 2025). "Regarding anxiety disorders, similar considerations to those previously made for depression can be made, especially regarding the role of AQP-4, astrocytes and neuroinflammation." (PMID 39234773, 2024). "Linear regression analysis was employed to investigate the relationships between AQP4-ON and vision-related QoL, as well as depression." (PMID 37840923, 2023). "Our findings suggested that inhibiting AQP4 impaired the glymphatic system and induced depression-like behaviors." (PMID 37802998, 2023). "This neuroinflammatory pathway, along with the classical pathway of defective monoaminergic neurotransmission (regulated by AQP4 and impacted by the established pro-inflammatory habitus), represents the pathogenetic pivot of major depressive disorder (MDD)." (PMID 37508493, 2023).